FGF21 (fibroblast growth factor 21)
Diseases named in the same sentence as FGF21 in open-access papers (continued):
Sharing a sentence is not in itself a finding about the gene and the disease.
metabolic disease (continued). "Several studies have indicated that endocrine FGFs, especially FGF15/19 and FGF21, are attractive therapeutic target molecules for the treatment of metabolic disorders." (PMID 35159314, 2022). "Over recent years, increasing research attention has focused on FGF21 owing to its potential as a therapeutic agent for the treatment of metabolic diseases." (PMID 35935824, 2022). "Since protein restriction was correlated with metabolic and aging-related diseases, the role of FGF-21 in protein restriction and metabolic diseases/aging has been an important topic in recent years (Cluster ID #0)." (PMID 36238554, 2022). "Identifying the role of sex as a biological variable influencing the metabolic response to FGF21, therefore, has broad implications for the targeted application of nutritional and pharmacological treatments for metabolic disease." (PMID 35998055, 2022). "Recombinant FGF21 and FGF21 analogs have emerged as promising therapeutic drug candidates for metabolic disorders, including NAFLD, and are currently in clinical development for the potential treatment of NASH." (PMID 36012166, 2022). "FGF21 is a promising drug candidate for the treatment of metabolic diseases, such as type 2 diabetes, obesity and nonalcoholic steatohepatitis." (PMID 35628302, 2022). "Previous studies have evaluated the effects of chronic exercise on FGF21 levels in patients with metabolic diseases." (PMID 33498410, 2021). "These properties inspired great enthusiasm for development of FGF21-based therapies for treatment of metabolic disease." (PMID 34917032, 2021). "The elevation of FGF21 levels in metabolic disorders has been inferred as a compensatory response to attenuate glucose and lipid dyshomeostasis via exerting insulin-sensitizing and triglyceride-lowering effects." (PMID 33668309, 2021). "In the second part, the influence of nutrition on FGF21 expression and the role of FGF21 for metabolic diseases in dairy cows is addressed." (PMID 34517929, 2021). "As FGF21 has attracted increasing attention as a target for metabolic diseases, clarifying its role in humans is pivotal." (PMID 34141520, 2021). "A convincing relationship between FGF21 and the development of metabolic diseases in dairy cows has been established for fatty liver and ketosis." (PMID 34517929, 2021). "This review aims to interpret the interactive influence between FGF21, aging, and metabolic diseases and delineate the pharmacology of FGF21, providing theoretical support for further research on FGF21." (PMID 33869312, 2021). "FGF21, as a potential stimulus to improve metabolic diseases, is a powerful metabolic regulator of mitochondrial dysfunction." (PMID 33498410, 2021). "FGF21 is known to be a key mediator of energy homeostasis and inflammatory processes in metabolic diseases, and its concentration changes in healthy and unhealthy conditions." (PMID 34762789, 2021). "I hope this review, which summarizes many previous studies, can help promote more research on FGF21 in aging-related metabolic disorders." (PMID 33869312, 2021). "Taken together, there was a promising role of FGF-21 in coordinating the metabolic responses to reverse nutritional stress as well as a valuable biomarker for predicting a variety of metabolic disorders." (PMID 33810243, 2021). "We then provide experimental evidence that increased FGF21 production induced by altered mRNA translation kinetics is the likely initial perturbation that increases FGF21 levels in metabolic diseases." (PMID 34141520, 2021). "In conclusion, we identified an unanticipated mechanism that helps to reconcile the apparently contradictory reports regarding the significance of elevations in FGF21 in the context of metabolic diseases." (PMID 34141520, 2021).
metabolic disease (continued). "Although complex in its function and regulation, the current integrative physiological role of FGF21 is as a key regulator in the adaptation to stress that can limit the progression of metabolic disease states with the goal of restoring homeostasis." (PMID 33762965, 2021). "Viewed collectively, it appears that these unresolved issues will delay implementation of FGF21-based mimetics for broad-based treatment of metabolic disease for now." (PMID 34917032, 2021). "Paradoxically, fibroblast growth factor 21 (FGF21) levels—a hormone with beneficial effects on metabolism—are elevated in metabolic diseases." (PMID 34141520, 2021). "Elevated levels of FGF21 in serum during the early stages of various metabolic diseases are considered a compensatory response by the organism." (PMID 34573919, 2021). "The discrepancies include circulating FGF21 levels, tissue-specific expression and regulation, and its role in glucose and lipid metabolism in addition to metabolic diseases." (PMID 33762965, 2021). "At present, FGF21, deemed as a metabolism-related hormone, is an emerging therapeutic target for metabolic diseases." (PMID 34675822, 2021). "Collectively, these studies with pre-clinical models provided a compelling rationale for developing FGF21-based pharmacotherapies for metabolic disease." (PMID 34917032, 2021). "This implies that an early and perhaps primary event in FGF21 alterations with the onset of human metabolic diseases is increasing genotype‐dependent FGF21 production rather than decreased peripheral tissue sensitivity." (PMID 34141520, 2021). "FGF-21 controls glucose and lipid metabolism and has thus been identified as a potential therapeutic target for metabolic disease." (PMID 34659937, 2021). "The increased levels of FGF21 in metabolic disorders are suggestive of FGF21 resistance, similar to that of insulin and leptin." (PMID 32372975, 2020). "Fibroblast growth factor 21 (FGF21) is in biomedical focus as a treatment option for metabolic diseases, given that administration improves metabolism in mice and humans." (PMID 32714278, 2020). "Together, these effects on adipose tissue and skeletal muscle contribute to the role of FGF21 in mediating protection against metabolic disease in numerous models." (PMID 33381084, 2020). "We conclude that long-term activation of mTORC1 by LTsc1KO, upstream regulators (Dddit4) of mTORC1 was impaired; meanwhile, expression of downstream genes (Nupr1 and FGF21) of mTORC1 was decreased, resulting in metabolic disorder and mitochondrial defects." (PMID 32363190, 2020). "We anticipate that these results will spur further investigation into GLP-1/FGF21 multiagonism for the treatment of metabolic disease." (PMID 32923621, 2020). "PPARs and PGC-1α (peroxisome proliferator-activated receptor γ coactivator 1-α) modulate FGF21 function, and a previous study showed that PPARα agonists ameliorated metabolic disorders in obese mice through modulation of FGF21 expression." (PMID 33086679, 2020). "The most prevalent and consistent dose-limiting side effects observed across studies of FGF21 analogs in patients with metabolic disease are gastrointestinal (GI), including mild-to-moderate nausea and diarrhea." (PMID 33381084, 2020). "In this review, we summarize preclinical and clinical data from studies with FGF21 and FGF21 analogs, in the context of the pathophysiology of NASH and underlying metabolic diseases." (PMID 33381084, 2020). "Although bariatric surgery can effectively reduce weight and resolve T2DM and metabolic diseases, reports about the changes in FGF21 after bariatric surgery are controversial." (PMID 32210348, 2020). "Recombinant human Fibroblast growth factor 21 (rhFGF21) is an endocrine hormone that has profound effects on treatment of metabolic diseases." (PMID 30691455, 2019).
metabolic disease (continued). "Identified as the 21st member of FGF superfamily in 2000, the endocrine hormone fibroblast growth factor 21 (FGF21) has attracted considerable attention regarding the management of metabolic diseases as well as their complications." (PMID 31511499, 2019). "In particular, recombinant human fibroblast growth factor 21 (rhFGF21) has been a focus of investigation as a new drug candidate for metabolic diseases." (PMID 30691455, 2019). "Since FGF21 has different characteristics from other metabolic regulators, FGF21 gains attention as an agent to treat metabolic disease." (PMID 30984550, 2019). "Taken together, FGF21, from physiological and clinical perspectives, is a potential biomarker for the early detection of human metabolic disorder." (PMID 31582974, 2019). "Our results are inconsistent with previous studies regarding the beneficial effects of FGF21 against metabolic disease." (PMID 31408968, 2019). "Metabolic disorder was ameliorated by metformin via induction of fibroblast growth factor 21 (FGF21) in adipose tissue." (PMID 31788033, 2019). "All these findings will become clear when FGF21 will be used as a therapeutic molecule, exploiting the beneficial effects of FGF21 for treating metabolic disease or when it will be blocked to ameliorate disease progression and the onset of disease." (PMID 31057418, 2019). "Metabolic disorders or chronic stress involving inflammatory responses would provoke FGF21 secretion as a compensatory response." (PMID 30127382, 2018). "Pharmacological administration of FGF21 analogues has shown robust body weight reduction and lipid profile improvement in both dysmetabolic animal models and metabolic disease patients." (PMID 29523796, 2018). "In a recent review the application of FGF21 analogues for the treatment of metabolic disorders and NAFLD has been summarized." (PMID 30547786, 2018). "The purposes of our study were to evaluate variations of serum ANGPTL4 and FGF21 concentrations in periparturient dairy cows and changes in these serum analyte concentrations of energy-related metabolic disorders in early lactation dairy cows." (PMID 30103741, 2018). "More importantly, 39F7 offers promising therapeutic potential in the axis of FGF21 signaling as an antibody therapy alternative to FGF21 analogs for treatment of metabolic diseases." (PMID 30068552, 2018). "Our findings in this current study provide novel insights in understanding the role of FGF21 in metabolic diseases." (PMID 29854743, 2018). "FGF21 thus holds promise as an excellent drug target for the treatment of metabolic diseases characterizing impaired glucose homeostasis." (PMID 28225059, 2017). "FGF-21, a member of the fibroblast growth factor group, is a well-recognized metabolic and a promising target in managing metabolic diseases." (PMID 29036766, 2017). "Combining these suggestions, this study proposed to investigate the role of the FGF-21-PGC-1 alpha-irisin axis in metabolic disease and sarcopenia." (PMID 29036766, 2017). "The FGF21 level is higher under stressful conditions, including starvation and high fat diet, and FGF21 improves metabolic disorder under these conditions." (PMID 27455076, 2016). "To further analyze the relationship between serum FGF21 levels and metabolic disorders, we assessed its correlation with serum lipids, glucose, and insulin." (PMID 27190511, 2016). "Exogenous FGF21 administration increased insulin sensitivity in several animal models of metabolic diseases." (PMID 26092866, 2015). "Although the precise function of FGF-21 is still unclear, this molecule is currently regarded as a useful biomarker of metabolic disorders." (PMID 26382974, 2015). "An FGF21 therapeutic represents an attractive opportunity for novel drug development treating metabolic disorders." (PMID 26594197, 2015).
metabolic disease (continued). "Serum levels of FGF-21 increased and correlated with alanine transaminase, γ guanosine-5′-triphosphate, and total cholesterol only in smokers, suggesting FGF-21 as a metabolic disorder-related factor in smokers." (PMID 26382974, 2015). "Since there are no prior studies that address the influence of smoking on the correlation between FGF-21 and metabolic disorders, further studies are definitively needed to clarify these relationships." (PMID 26382974, 2015). "The beneficial effects of native FGF21 and FGF21 analogues in normalizing glucose and lipid homeostasis have been demonstrated in a variety of preclinical metabolic disease models, including DIO mice, ob/ob mice, db/db mice, diabetic NHP and obese NHP." (PMID 25790234, 2015). "FGF21 expression is strongly induced in animal and human subjects with metabolic diseases, but little is known about the molecular mechanism." (PMID 24900988, 2014). "At present, FGF21 is considered as a novel metabolism regulator and has become a focus of metabolic disease research." (PMID 24900988, 2014). "We then demonstrated that TG-induced ER stress upregulates the expression and secretion of FGF21 by influencing ATF4 and CHOP, providing insights on the mechanisms that link FGF21 and metabolic diseases." (PMID 24900988, 2014). "FGF21 is a metabolic regulator has many beneficial effects on cell metabolism and in human metabolic diseases." (PMID 25932355, 2014). "Serum FGF21 level significantly elevated with the increasing number of metabolic disorders (P for trend < 0.01)." (PMID 23981342, 2013). "Mainly characterized as a metabolic factor, the newly-recognized cytokine characteristics of FGF21 have stimulated research interest in its putative roles in the inflammation-related processes of metabolic disorders and diseases." (PMID 23981342, 2013). "Fibroblast growth factor 21 (FGF21) is a novel metabolic regulator that represents a promising target for the treatment of several metabolic diseases." (PMID 23823755, 2013). "The therapeutic potential of both FGF19 and FGF21 in the treatment of metabolic disorders has been discussed extensively in the literature." (PMID 22675463, 2012). "The identification of FGF21 as a metabolic regulator has triggered extensive study in part due to the therapeutic potential of FGF21 to treat metabolic disease." (PMID 23209629, 2012). "Manipulation of expression or pharmacological administration of FGF19 or FGF21 protein in mice has major impact on metabolic diseases and pathways in hepatocytes in addition to adipocytes." (PMID 23106963, 2012). "There is significant interest in developing FGF21 as a therapeutic agent to treat metabolic diseases." (PMID 23209571, 2012). "As one of fibroblast growth factor (FGF) family members, FGF21 has been extensively investigated for its potential as a drug candidate to combat metabolic diseases." (PMID 21673953, 2011). "Several excellent review articles on FGF21, focusing on its pharmacological effects on metabolism and therapeutic uses for metabolic diseases have been published." (PMID 21331285, 2011). "In recent years, FGF21 has been described as potential new drug candidate to combat metabolic diseases." (PMID 20163718, 2010). "Despite these metabolic benefits, elevated FGF21 levels in metabolic disorders may reflect FGF21 resistance or a compensatory response to metabolic stress." (PMID 41186080, 2025). "In light of these positive downstream influences, the presence of elevated FGF-21 across a range of metabolic diseases suggests that MASLD may represent a state of relative FGF-21 resistance." (PMID 40408301, 2025). "Consequently, FGF21 has emerged as a promising therapeutic for treating metabolic diseases, given its beneficial effects on metabolic regulation." (PMID 39884432, 2025). "Research has shown that FGF21 can alleviate many age-related metabolic diseases." (PMID 40110129, 2025).
metabolic disease (continued). "FGF21, a growth factor involved in different metabolic disorders and neurodegenerative disorders, exhibits neuroprotective effects against neurodegenerative diseases through inhibition of mitochondrial dysfunction, cerebrovascular aging, and associated inflammatory and oxidative stress disorders." (PMID 40172524, 2025). "Additionally, in metabolic disorders, FGF-21 alleviates mitochondrial stress by regulating the ERK1/2 pathway and modulating activating transcription factor 5 (ATF5) and C-Myc expression." (PMID 40437610, 2025). "According to these findings, FGF21 might act as an early subclinical indicator of metabolic diseases." (PMID 39452947, 2024). "Given the therapeutic potential of FGF21 analogues in metabolic disease, the selective activation of the FGF21 signalling axis in cardiomyocytes by exercise to induce SIRT3 may be an effective strategy for treating various heart diseases." (PMID 37845840, 2024). "Notably, among them, FGF21 and adiponectin have gained considerable attention due to their diverse protective effects against a range of metabolic disorders." (PMID 39408777, 2024). "Previous studies on FGF21 have focused on its role in various metabolic diseases." (PMID 37864659, 2024). "Increased FGF21 levels may indicate the body’s response to metabolic stress, which could be a target for treating metabolic disorders and cardiovascular diseases." (PMID 39194718, 2024). "We propose that the in-silico workflow used to successfully predict experimentally verified stabilized FGF21 mutants with uncompromised biological activity can be used in combination with other reported strategies to improve the potential of FGF21 as metabolic disease therapeutics." (PMID 38379823, 2024). "Another study revealed that plasma FGF21 levels are associated with increased pericardial fat deposition, suggesting that ectopic fat could be a source of FGF21 in metabolic diseases." (PMID 39519454, 2024). "The results of recent studies suggested that FGF21 may be an effective drug for treating metabolic disorders." (PMID 38139126, 2023). "Thus, in phase I and II clinical trials, several companies have tested FGF21 analogs created with different technologies in healthy humans or those with metabolic disorders." (PMID 37948566, 2023). "The current study provided an option to adopt FGF21 therapy in metabolic diseases." (PMID 36793871, 2023). "Notably, beyond the clinical application of FGF21-based drugs, FGF21 has great potential as a biomarker for metabolic disease diagnosis and prognosis." (PMID 36594101, 2023). "This study may additionally support the hypothesis that HFrEF is, in part, a metabolic disease with alterations in fuel signalling proteins such as FGF21 from extracardiac organs such as the liver engendering changes in cardiac energy metabolism." (PMID 36028609, 2023). "Given that FGF21 improves metabolic disorders, this study indicates that the strategies to increase intracellular pyruvate levels in hepatocytes may benefit form metabolic disorder therapy." (PMID 35628302, 2022). "Thus, FGF21 has been a promising drug candidate for treating metabolic diseases, such as type 2 diabetes, obesity, and nonalcoholic steatohepatitis." (PMID 36045720, 2022). "Multiple FGF21 analogues have been developed for treating metabolic diseases." (PMID 36362103, 2022). "Assuming a state of FGF21 resistance in metabolic diseases the question is whether this state can be reversed." (PMID 36235821, 2022). "Therefore, further understanding of the mechanisms involved in the metabolic regulation attributed to targeting FGF21 is necessary, which will facilitate the development of more effective and safer drugs for the treatment of metabolic diseases." (PMID 36618930, 2022). "Also, despite the few studies that have been done on the genetic variations of FGF21, significant results have been obtained regarding the direct and indirect effects of these variations on metabolic diseases." (PMID 36457562, 2022).